FLT1 (fms related receptor tyrosine kinase 1)
Diseases named in the same sentence as FLT1 in open-access papers (continued):
Sharing a sentence is not in itself a finding about the gene and the disease.
atherosclerosis (13 papers, 2013 to 2025). A disease characterized by the build-up of fatty material and calcium deposition in the arterial wall resulting in partial or complete occlusion of the arterial lumen. "We have reported that activation of the PlGF/Flt-1 pathway caused by a reduction in sFlt-1 expression levels leads to atherosclerosis in patients with CKD." (PMID 31666542, 2019). "Both miR-200c-3p and miR-100-5p have the FLT1 gene as a predicted target—this gene is closely involved in vascular integrity and is regarded as a candidate atherosclerosis gene." (PMID 39337512, 2024). "In arthritis and atherosclerosis, anti-FLT1 antibody impaired infiltration of FLT1-expressing leukocytes in inflamed tissues, thereby ameliorating the disease progression." (PMID 23977149, 2013). "Regarding the cardiovascular system, AST-120 was found to delay atherosclerosis in a uremic atherosclerosis mouse model by preventing the reduction of soluble fms-like tyrosine kinase 1 (Flt1) (an antiangiogenic factor whose expression is usually suppressed by uremic toxins in vitro)." (PMID 35448854, 2022). "A previous study demonstrated that the low-expression of Flt-1 may predict the occurrence of endothelial injury, which subsequently results in the occurrence of atherosclerosis." (PMID 31487691, 2019). "VEGFR-1/Flt-1 is expressed not just by endothelial cells but also by macrophages, promoting their function, and, via kinase activity, is involved in atherosclerosis, inflammatory diseases, and cancer metastasis." (PMID 37178326, 2023).
breast tumors (13 papers, 1999 to 2025). "In our retrospective analyses of human breast tumors with BRCA1/2 or PALB2 mutations from patients, we observed a strong association between FLT1 activation in human tumor cells at pre-treatment and subsequent development of PARPi resistance." (PMID 38956205, 2024). "We demonstrate that FLT1 blockade suppresses AKT activation, increases tumor infiltration of CD8+ T cells, and causes dramatic regression of PARPi-resistant breast tumors in a T-cell-dependent manner." (PMID 38956205, 2024). "In contrast, our findings suggest an underlying regulating mechanism through PDGF-D and FLT1, driven by PIK3CA mutation in breast tumors." (PMID 28392480, 2017). "To investigate how FLT1 activation in breast tumor cells counteracts PARPi-induced cytotoxicity, we first examined whether downstream mediators of the FLT1 pathway are activated in PARPi-resistant tumors." (PMID 38956205, 2024). "Moreover, patients with BRCA1/2- or PALB2 (partner and localizer of BRCA2)-mutant breast tumors that display heightened FLT1 expression in their tumor cells at pre-treatment are at high risk for progression on PARPi." (PMID 38956205, 2024). "Based on those phosphorylation patterns, a computational upstream kinase analysis predicted increased activity of PTKs that are known to contribute to invasive progression and metastasis of breast tumor, namely, FLT4, JAK1b, TRKB, and FLT1." (PMID 35847979, 2022).
Hyperglycemia (13 papers, 2014 to 2026). An increased concentration of glucose in the blood. "Db/db mice with pressure ulcers showed an impairment in the molecular regulation of hypoxia-related genes (Hif1a, Flt1, and Kdr), while extracellular matrix encoding genes (Itgb3, Timp1, Fn1, Col4a1) were upregulated by hyperglycemia and lesions." (PMID 35386010, 2022). "Under these conditions, neutrophils are the main producers of VEGF and induce FLT‐1 expression, suggesting that hyperglycemia disrupts the VEGF/FLT‐1 balance." (PMID 41508422, 2026). "We demonstrated that hyperglycaemia inversely modified FLT-1 protein level in DRG neuron monocultures (where it increased) and SC (where it decreased)." (PMID 25268360, 2014). "We demonstrated that hyperglycaemia early affected neurite outgrowth through the impairment of SC-derived VEGF/FLT-1 signaling and that the neutralization of SC-secreted VEGF was protective both in vitro and in vivo models of diabetic neuropathy." (PMID 25268360, 2014). "The presence of hyperglycemia disrupts the balance of angiogenic receptors and ligands (VEGF and FLT-1), potentially leading to chronic inflammation, hypoxia, and inhibition of burn wound healing." (PMID 40419622, 2025). "Placentas from women with hyperglycemia contain high levels of VEGF and VEGF receptor 2 (KDR), but reduced expression of VEGF receptor 1 (Flt-1) compared to normoglycemic women." (PMID 28817576, 2017). "Conversely, exposition of hyperglycaemia-conditioned SC monocultures to bevacizumab increased FLT1 protein and reduced FLT-1 mRNA." (PMID 25268360, 2014). "Moreover, hyperglycemia alters normal placental function by reducing expression of VEGF-A, VEGFR-1/Flt-1 and PIGF in placenta and serum of diabetic mothers." (PMID 27186496, 2016). "At the same time, hyperglycaemia significantly decreased FLT-1 protein level in SC monocultures (relative protein expression 61±11 vs ctrl 100), whereas FLT-1 protein level remained unchanged in neuron monocultures (55±28 vs ctrl 100) and DRG co-cultures (168±92 vs ctrl 100)." (PMID 25268360, 2014). "Exposition of hyperglycaemia-conditioned DRG neuron monocultures to bevacizumab normalized FLT-1 mRNA with no change at the protein level." (PMID 25268360, 2014). "Microarray studies showed that the mRNA of VEGFR1 (alias FLT1) was upregulated (1.7-fold, p = 7.36 × 10−3) under euglycemia-CoCl2 at 12 h of CoCl2 but not under hyperglycemia-CoCl2." (PMID 29351188, 2018). "Hyperglycaemia increased VEGF and FLT-1 mRNA without changing their intracellular protein levels in DRG neurons, decreased intracellular and secreted protein levels without changing mRNA level in SC, while reduced the expression of the soluble receptor sFLT-1 both in DRG neurons and SC." (PMID 25268360, 2014).
ischemia (13 papers, 2010 to 2024). A hypoperfusion of the BLOOD through an organ or tissue caused by a PATHOLOGIC CONSTRICTION or obstruction of its BLOOD VESSELS, or an absence of BLOOD CIRCULATION. "The C5.0 decision tree indicates that cardiac grafts from the ischemia+AAT (1h and 5h after ischemia) are associated with increased expressions of myocardial Flt1, Cflar, and Bcl2, hence supporting the protective effects of AAT." (PMID 37426668, 2023). "Next, we utilized the C5.0 decision tree to display the criteria for splitting used in the inter-group classification: 1) if Flt1 expression is ≤ 23.029 and Gpx3 expression is ≤ 20.448, the cardiac graft belongs to either the 1h ischemia or 5h ischemia groups." (PMID 37426668, 2023).
lung adenocarcinoma (13 papers, 2012 to 2025). A carcinoma that arises from the lung and is characterized by the presence of malignant glandular epithelial cells. "miR-200 inhibits lung adenocarcinoma cell invasion and metastasis by targeting Flt1/VEGFR1 in a mouse model, while miR-221 and 222 enhance cellular migration through activation of the AKT pathway." (PMID 22408395, 2012).
endometriosis (12 papers, 2013 to 2025). The growth of functional endometrial tissue in anatomic sites outside the uterine body. "RSPO3 and FLT1 were found to be potentially associated with endometriosis within the proteome." (PMID 40893937, 2025). "FLT1 and SCN11A were up-regulated and GNLY was down-regulated, suggesting that endometriosis is associated with an inflammatory response." (PMID 33868805, 2021). "Whereas, in the differentially expressed gene analysis, the tumor related genes TEX41, POLQ, and FLT1 were highly expressed in the ectopic endometrial cell group of endometriosis, and the expression of tumor suppressor gene PLCD1 was down-regulated when compared with the control group." (PMID 33868805, 2021). "This proangiogenic milieu is reinforced by reduced concentrations of antiangiogenic factors, such as adiponectin and interferon-gamma-induced protein 10 (IP-10), although levels of the endogenous VEGF antagonist soluble Flt-1 were reported to be increased in the pelvic fluid of endometriosis cases." (PMID 23766765, 2013).
Arthritis (11 papers, 2008 to 2025). Inflammation of a joint. "FLT-1 expression in arthritis is stimulated by two the most important proinflammatory cytokines - IL-1β and TNF-α, which can mediate the progression of bone destruction." (PMID 28323906, 2017). "Investigations on the effect of anti-Flt-1 peptide GNQWFI on an experimental model of arthritis are under way." (PMID 19223981, 2008). "Interestingly, the failure of anti-KDR Ab, but not of anti-Flt-1 Ab, to block arthritis and atherosclerosis, indicates that anti-inflammation, rather than antiangiogenesis, may be primarily responsible for the observed effects of anti-VEGF Ab." (PMID 19223981, 2008).
COVID-19 (11 papers, 2020 to 2024). A disease caused by infection with severe acute respiratory syndrome coronavirus 2. "Soluble levels of Flt-1 (sFlt-1), a circulating truncated form of the VEGF-A receptor-1 (VEGFR-1/Flt-1), were markedly increased in COVID-19 patients and paralleled disease severity." (PMID 36140343, 2022). "The vasodilating and permeability factor VEGF-A and its endogenous inhibitor sFlt-1, a truncated and circulating form of the VEGF-A receptor Flt-1, were markedly increased in COVID-19 patients and correlated with disease severity." (PMID 33058027, 2021). "The use of the s-Flt1/PlGF ratio in COVID-19 as a clinical tool to stratify the intensity of endothelial dysfunction has been proposed in this study." (PMID 32848893, 2020). "Therefore, dysregulation of the renin/angiotensin system is a potential unifying mechanism for our findings of increased Tie-2 and Flt-1 in post-COVID-19 patients." (PMID 36844209, 2023). "Among elevated plasma inflammatory mediator levels; CRP, ICAM-1, SAA, VCAM-1, CXCL10, IL-7, IL-10 and Flt-1 may suggest the severity of COVID-19." (PMID 35958594, 2022). "VEGF upregulation is also related to COVID-19 progression factors, where elevated levels of the VEGF-A Flt-1/VEGFR-1 complex are correlated with disease severity." (PMID 36992415, 2023). "In this study we found persistent elevation of multiple mediators – IL-6, TNFα, SAA, Tie-2, Flt1, PIGF, and CRP – and persistent depression of IL-7 and bFGF in patients recovering from COVID-19 several months following their acute infection." (PMID 36844209, 2023). "The findings showed that compared to healthy controls, patients with COVID-19 had significantly higher levels of interleukins 1α, 2, 6, 7, 8, 10 and 15, CRP, SAA, ICAM-1, VCAM-1, CXCL10, CCL3, CCL26, IFN-γ, TNF-α, bFGF, PlGF, and Flt-1." (PMID 35958594, 2022). "Compared to the healthy controls, patients with COVID-19 had significantly higher circulating concentrations of 19 inflammatory mediators, namely interleukins 1α, 2, 6, 7, 8, 10 and 15, CRP, SAA, ICAM-1, VCAM-1, CXCL10, CCL3, CCL26, IFN-γ, TNF-α, bFGF, PlGF and Flt-1 (P < 0.05)." (PMID 35958594, 2022).
rheumatoid arthritis (11 papers, 2008 to 2025). A chronic, systemic autoimmune disorder characterized by inflammation in the synovial membranes and articular surfaces. "Considering the important role of the FLT-1 in the modulation of angiogenesis and inflammatory processes as well as differences in genetic predispositions between populations we decided to carry out an analysis of selected FLT-1 gene polymorphisms in relation to rheumatoid arthritis." (PMID 28323906, 2017). "As an example, the binding of PlGF to Flt-1 in patients with rheumatoid arthritis stimulated the production of proinflammatory cytokines, including TNF-α and IL-6 in monocytes, enhancing inflammation." (PMID 40800007, 2025). "To understand the possible role of FLT-1 in patients with rheumatoid arthritis we also determined the sFLT-1 expression levels in serum; it was assessed in 153 RA patients and 252 healthy subjects recruit from the genetic study cohort, by ELISA." (PMID 28323906, 2017). "We also demonstrated that FLT-1 serum levels in RA patients were significantly higher than in controls, reflecting the angiogenesis and/or chronic inflammation in rheumatoid arthritis patients and trying to keep it under control." (PMID 28323906, 2017). "Flt-1 reduced OA and rheumatoid arthritis progression in animal models." (PMID 41050371, 2025). "The elevated expression of FLT1 may also pertain to the development of rheumatoid arthritis inflammation." (PMID 37109422, 2023).
type 2 diabetes (11 papers, 2013 to 2026). "Flt-1 has been found in higher concentrations in individuals with type 2 diabetes, but not in individuals with impaired fasting glucose." (PMID 39078488, 2024). "A previous study of 107 type 2 diabetic patients and 47 control subjects in South Korea showed higher urine soluble Flt-1 levels in diabetic patients in parallel with higher urinary VEGF-A and a positive relationship between urine soluble Flt-1 level and albuminuria." (PMID 29937525, 2018).
Alzheimer disease (10 papers, 2018 to 2025). A progressive, neurodegenerative disease characterized by loss of function and death of nerve cells in several areas of the brain leading to loss of cognitive function such as memory and language. "Higher prefrontal cortex expression of Flt1 was associated with worse cognitive trajectories in Alzheimer disease patients." (PMID 31652960, 2019). "Several biomarkers, including ADRD (Alzheimer’s disease and related dementias) biomarkers (Ab, tau, NfL, and GFAP) and angiogenic factors (VEGF, Flt-1, Tie-2, PIGF, and FGF) have been associated with the development of dementia." (PMID 41306424, 2025). "SPP1, CD44, IGF1, and FLT1 were identified as crucial molecules in the main cluster of Alzheimer’s disease and metabolic syndrome." (PMID 38809924, 2024). "Expression of vascular endothelial growth factor receptor 1 (Flt1) facilitates microglial chemotaxis to amyloid-β plaques in Alzheimer’s disease and may perform equivalent functions in rNLS8 late disease." (PMID 34412701, 2021). "Consistent with our results, findings have suggested that IGF1, FLT1, and CD44 may be involved in the development and progression of Alzheimer’s disease and MetS." (PMID 38809924, 2024).
endometrial cancer (10 papers, 2003 to 2025). Primary or metastatic malignant neoplasm involving the endometrium (mucous membrane that lines the endometrial cavity). "The results demonstrated that the prognostic capability of the XGboost-based radiomics model was achieved in part by revealing the level of blood supply in endometrial cancer, which was closely associated with FLT1 expression." (PMID 41023751, 2025). "The results showed that knockdown of FLT1 inhibited endometrial cancer cell migration, invasion, proliferation, and angiogenesis (after co-culture)." (PMID 41023751, 2025). "FLT1 has been proposed as a prognostic indicator in endometrial carcinoma." (PMID 33909629, 2021). "FLT1 has been shown to be a marker of angiogenesis in endometrial cancer, but its function as a predictor has not been determined." (PMID 31289124, 2019). "Unlike previous studies of endometrial cancer prognostic models, in this study, we correlated radiomics with Transcriptomics and Proteomics to find the biological function (angiogenesis) and possible molecular mechanism (FLT1) behind the Radiomics model." (PMID 41023751, 2025). "Vascular endothelial growth factor-1 binds VEGFR-1 (flt-1) but not VEGFR-2 (KDR), both of which are present in peritumoral endothelial cells of endometrial cancers." (PMID 12942123, 2003).
hemangioma (10 papers, 2010 to 2025). A benign vascular lesion characterized by the formation of capillary-sized or cavernous vascular channels. "VEGF, bFGF, flt-1, and flk-1 were immunohistochemically detected in the neoplastic cells in HSAs; the staining intensity was stronger in HSAs than in hemangiomas." (PMID 22888341, 2012).
leukemia (10 papers, 2012 to 2025). A malignant (clonal) hematologic disorder, involving hematopoietic stem cells and characterized by the presence of primitive or atypical myeloid or lymphoid cells in the bone marrow and the blood. "FLT1 has been evaluated as a target in other cancers (e.g., acute myeloid leukemia, leukemia, and chronic lymphocytic leukemia) and has been reported to be an important gene product in B-ALL." (PMID 41020821, 2025). "Furthermore, FLT-1 is generally expressed in pediatric ALL and VEGFA/FLT-1 signaling enhances the migration and survival of leukemia." (PMID 34980027, 2022). "In addition, FLT-1 neutralization affects leukemia localization, increases leukemia apoptosis, and impedes the exit of ALL cells, thus prolonging the survival of inoculated mice." (PMID 34980027, 2022). "Concurrently, Dovitinib, targeting FLT1, EGFR, FLT3 and KIT, acts as a EGFR inhibitor and FLT3 inhibitor, with previous research showing Dovitinib showed treatment efficacy in naïve and imatinib-resistant BCR::ABL(+) leukemia cells." (PMID 39247833, 2024). "Additionally, studies have eluded to the fact that not only VEGF signals through receptor expression VEGFR-1 (Flt-1) and VEGFR-2 (FlK-2/KDR) specifically regulate endothelial function, but are also involved in the growth regulation of subsets of tumor cells such as leukemia." (PMID 22566481, 2012). "Moreover, the up-regulation of genes involved in inhibition of apoptosis (e.g. MCL1) may promote the survival of leukemia cells with accumulated DNA damage and their expansion as suggested by an up-regulation of genes involved in cell cycle progression (AHR, AHR, TUBB2A, RAPGEF3, SERTAD1, FLT1)." (PMID 22848414, 2012).
lymph node metastasis (10 papers, 2007 to 2025). "The Flt-1 expression level in the patients with lymph node metastasis was 71.3%, significantly higher than that in the patients without lymph node metastasis (40%; P= 0.02)." (PMID 23946799, 2013). "The expression levels of VEGF and Flt-1 in the patients with lymph node metastasis were 85.7 and 78.6%, respectively, evidently higher than those in the patients without lymph node metastasis; the two differences were significant (P=0.009; P=0.02)." (PMID 23946799, 2013). "VEGF may have an important role in lymph node metastasis when combined with Flt-1." (PMID 23946799, 2013). "The co-expression levels of VEGF and receptor Flt-1 in malignant neoplasms with lymph node metastasis was significantly higher compared with malignant neoplasms without lymph node metastasis (P<0.05)." (PMID 23946799, 2013).
myocardial infarction (10 papers, 2011 to 2025). Gross necrosis of the myocardium, as a result of interruption of the blood supply to the area, as in coronary thrombosis. "Chronic bradycardia was shown to have a beneficial effect on coronary revascularization in rats with myocardial infarction by upregulation of several growth factors and their receptors, namely, VEGF, Flt-1, and bFGF." (PMID 21966411, 2011).
cardiac hypertrophy (9 papers, 2014 to 2025). "Our results show that relative activation of PlGF/Flt-1 by decreased sFlt-1 production plays a key role in the aggravation of cardiac hypertrophy and HF through upregulation of MCP-1 expression in the pressure-overloaded heart." (PMID 36430665, 2022). "In CKD it is likely that PlGF/Flt-1 signaling partly contributes to phenotypic changes of CKD such as ventricular hypertrophy and cardiac fibrosis with accumulation of macrophages and T cells in the heart, and smooth muscle cell proliferation and plaque formation in large arteries." (PMID 36430665, 2022).